AIM2 (absent in melanoma 2)
Diseases named in the same sentence as AIM2 in open-access papers (continued):
Sharing a sentence is not in itself a finding about the gene and the disease.
psoriasis (continued). "In psoriasis and atopic dermatitis, AIM2 expression was increased in both lesional and non-lesional skin, and, in psoriatic lesions, cytosolic DNA triggers AIM2 activation in keratinocytes; however, the source of cytosolic DNA in psoriatic keratinocytes remains unclear." (PMID 37443800, 2023). "For example, AIM2 might promote the proliferation of epithelial cells and regulate the function of Treg cells; both of these cells are instrumental cell types that execute important functions in psoriasis development." (PMID 36742336, 2023). "In addition to the role of the AIM2 inflammasome, AIM2 inflammasome-independent way may also play a significant role in the pathogenesis of psoriasis." (PMID 36742336, 2023). "AIM2 may also play a role in the recurrence of psoriasis by trained immunity." (PMID 36742336, 2023). "During IMQ-induced skin inflammation, the expression of AIM2 inflammasome components, such as AIM2, ASC, and pro-caspase-1, in skin lesions is upregulated, and serum levels of IL-17A, a cytokine which has been implicated in the pathogenesis of psoriasis, are increased." (PMID 36982727, 2023). "In an rIL-23-induced psoriasis mouse model, a TLR-7,−8, and−9 antagonist inhibited the dermal expression of Nlrp3 and Aim2 and reduced the secretion of Th1 and Th17 cytokines in skin and serum, suggesting that inflammasomes might be a therapeutic target for psoriasis treatment." (PMID 32528469, 2020). "In this study, we provide a comprehensive analysis of pyroptosis-related genes (PRGs) in psoriasis, identifying key molecular players such as CASP1, CASP5, AIM2, NOD2, and IL1B that drive the inflammatory response and disease progression." (PMID 40771724, 2025). "Research has indicated that the inflammasome inhibitor (NLRP2/AIM-3-IN-21) exhibited significant therapeutic potential in psoriasis, and effectively suppressed the expression levels of NLRP3, IL-17A, and AIM2 in psoriatic skin lesion tissues." (PMID 41383588, 2025). "Our analysis identified CASP1, CASP5, AIM2, NOD2, GZMB, GZMA, and IL1B as key hub genes in the inflammatory pathways driving psoriasis pathogenesis." (PMID 40771724, 2025). "However, it was still unclear whether AIM2 participates in developing psoriasis." (PMID 39352743, 2024). "Our team has demonstrated that cg07195224 is included in the promoter region of the AIM2 gene, which is the CPG site of significant hypomethylation in psoriasis." (PMID 36742336, 2023). "To further assess the function of TFH‐AIM2 in lupus, we examined the co‐localisation of TFH‐like cells and AIM2 in patients with discoid lupus erythematosus (DLE), SLE, psoriasis and NCs." (PMID 35343082, 2022). "Several types of inflammasomes are recognized, including NLRP1, NLRP3, and absent in melanoma 2 (AIM2), in the pathogenesis of psoriasis." (PMID 35663672, 2022). "The AIM2 total fluorescence intensity in CD4+ Trm cells in patients with SCLE and localized DLE were higher than in patients with psoriasis." (PMID 36118867, 2022). "Treatment with TLR-7, -8, and -9 antagonists in these mice was shown to reduce both psoriasis-related skin lesions, inhibit the dermal expression of NLRP3 and AIM2, and decrease the secretion of Th1 and Th17 cytokines in the skin and serum." (PMID 34072753, 2021). "A relevant role of AIM2 in keratinocytes was demonstrated during human papillomavirus (HPV) infection and in psoriasis." (PMID 34777694, 2021). "The study shows that patients with psoriasis have increased plasma levels of IL-1β and IL-18 and increased constitutive expression of the inflammasome sensors NLRP3, NLRP1, and AIM2 in peripheral blood cells, together with increased caspase 1 reactivity." (PMID 34502368, 2021). "In this review, from the perspective of activators and inhibitors, we collected evidence from the widely-studied inflammasomes, NLRP3, AIM2, and NLRP1, in psoriasis, vitiligo, SLE, and AD." (PMID 32528469, 2020).
psoriasis (continued). "Upon activation, both AIM2 and NOD2 trigger the formation of inflammasomes that ultimately lead to CASP1 activation, which processes pro-inflammatory cytokines such as IL-1β, which is also a key player in psoriasis through our former analysis." (PMID 40771724, 2025). "Also, AIM2 and NOD2 are key players in pyroptosis (hub genes) identified through our analysis in psoriasis." (PMID 40771724, 2025). "We demonstrated that AIM2 functions through its canonical activation pathway involving ASC and caspase-1 inducing the generation of the IL-23/IL-17 immune axis required for developing psoriasis." (PMID 39352743, 2024). "To further explore the importance of AIM2 in psoriasis, we used the psoriasiform skin inflammation model triggered by the topical application of IMQ, a TLR7/8 agonist widely used to induce a murine model of psoriasis." (PMID 39352743, 2024). "We then evaluated AIM2 expression in skin biopsies from healthy volunteers and compared it with lesioned and nonlesioned areas of patients with psoriasis in 4 different NCBI GEO databases." (PMID 39352743, 2024). "Furthermore, in the context of AIM2 in keratinocytes and psoriasis, LL37 peptides were shown to inhibit AIM2 dsDNA sensing." (PMID 37187738, 2023). "Additionally, we identified 10 key genes including AIM2, BAK1 and CASP1, and confirmed the accuracy of these key genes in diagnosing psoriasis." (PMID 37861483, 2023). "However, the contribution of AIM2 in modulating the immune response during the development and persistence of psoriasis has not yet been elucidated." (PMID 39352743, 2024). "Even though whether AIM2 PANoptosome plays roles in psoriasis has not been determined, we still think AIM2 might be a good target for drug development in the future." (PMID 36742336, 2023). "The expression level of AIM2 gene in CD4+ tissue-resident memory T (CD4+ Trm) cells was measured in the patients with acute cutaneous lupus erythematosus (ACLE), subacute CLE (SCLE), localized discoid lupus erythematosus (localized DLE), psoriasis, and other inflammatory skin diseases." (PMID 36118867, 2022). "Indeed, PRRs were implicated in the pathophysiology of other inflammatory skin diseases, such as AIM2 (absent in melanoma 2) and dectin-1 in psoriasis." (PMID 26198339, 2015). "The highly expressed AIM2 level and increased AIM2‐TFH cells in SLE but not in other diseases like psoriasis or healthy people, suggested a potential of AIM2 as a biological marker in the diagnosis of SLE." (PMID 35343082, 2022). "Based on our results; AIM2 and IFI16 are highly expressed inflammasome receptors in psoriasis, whereas NLRP3 was not among the DEGs." (PMID 26976200, 2016). "Furthermore, mRNA of NLRP1, NLRP3, AIM2, PYCARD and CASP1 was observed in both lesional and non-lesional epidermis of psoriasis patients." (PMID 37325658, 2023). "Patients with psoriasis present relatively high plasma levels of inflammasome-generated IL-1β and high expression of inflammasome components such as NLRP3, NLRP1, and absent in melanoma 2 (AIM2)." (PMID 37964882, 2023). "Remarkably, only lupus patients but not psoriasis patients or NCs had high AIM2 expression among infiltrating CD4+ T cells in skin lesions, which suggested highly expressed AIM2 may contribute to lupus pathology." (PMID 35343082, 2022).
lupus (44 papers, 2011 to 2026). "AIM2 deficiency in B cells alleviated lupus symptoms and reduced the frequency of CD19+ cells in lymph nodes and spleen, as well as splenic GC B cells and plasmablasts/plasma cells of lymph node via Blimp1-Bcl-6 axis in pristane-induced lupus mice." (PMID 39917309, 2025). "All these murine findings confirmed that loss of CD4+ T‐cell‐intrinsic Aim2 ameliorated lupus symptoms by regulating the TFH response." (PMID 35343082, 2022). "All these data suggested Aim2 deficiency in CD4+ T cells ameliorated lupus features in pristane‐induced lupus model." (PMID 35343082, 2022). "In a pristane-induced mouse model of lupus, AIM2 deficiency in B cells attenuates lupus symptoms and reduces the frequency of GC B cells, T follicular helper (Tfh) cells, plasmablast cells, and plasma cells." (PMID 34521812, 2021). "Similar to IFI16‐β, mouse p202, a lupus susceptibility factor, interacts with AIM2 and halts dsDNA‐dependent caspase activation." (PMID 34014039, 2021). "In recent years, two ALR family members, the interferon (IFN)-inducible protein 16 (IFI16) and AIM2, have been linked to the pathogenesis of various autoimmune diseases, among which systemic lupus erythematosus (SLE) has recently gained increasing attention." (PMID 29892303, 2018). "Of interest, IFi202a is a candidate lupus susceptibility gene and p202a acts to negatively regulate the AIM2 inflammasome and several transcription factors including NF-κB and AP-1." (PMID 23826184, 2013). "Conditions such as Aicardi-Goutières syndrome and systemic lupus erythematosus have shown association with DNA sensing mechanisms, such as AIM2, and it is possible that DNA-PK, or other DNA sensors, contributes to the disease process." (PMID 24098118, 2013). "Similarly, mice receiving Aim2‐deficient cells showed milder clinical lupus symptoms, including less proteinuria and serum anti‐dsDNA antibody and ANA levels." (PMID 35343082, 2022). "Indeed, in our KLH model and pristane-induced lupus model, the loss of AIM2 in B cells finally resulted in the reduced frequencies of GC B cells, Tfh cells, plasmablast cells, and plasma cells." (PMID 34521812, 2021). "However, there is also contradictory evidence showing that AIM2 was negatively associated with inflammation in lupus." (PMID 31427885, 2019). "Therefore, AIM2 protein is expected to become a novel target for reducing lupus susceptibility." (PMID 35693810, 2022). "Additionally, AIM2 deficiency in B cells modulates B-cell differentiation through the Blimp-1-Bcl-6 axis, leading to the amelioration of systemic lupus erythematosus (SLE)." (PMID 39076969, 2024). "Reduced AIM2 expression can decrease B cells in the GC and alleviate lupus symptoms, highlighting the role of GC in lupus disease." (PMID 38022566, 2023). "POU2F2/OCT2, important for generation of ASCs; SWAP70, shown to influence ABC expansion; and AIM2, which positively regulated expansion of autoreactive B cells in a mouse lupus model, were increased in both blood and skin B cells in active cGVHD." (PMID 37129971, 2023). "However, aberrant activation of AIM2 can cause immune-related diseases such as systemic lupus erythematosus (SLE), psoriasis, primary Sjögren’s syndrome, and arthritis." (PMID 37608944, 2023). "The AIM2 inflammasome can restrict the replication of bacteria and is involved in the pathogenesis of autoimmune diseases, such as systemic lupus erythematosus (SLE) and lung tumorigenesis." (PMID 37122745, 2023). "The same research team also recently revealed higher AIM2 expression in memory B cells and plasma cells from the circulation and skin lesions of lupus patients." (PMID 35538881, 2022). "It was also found that the expression of AIM2 in peripheral blood mononuclear cells (PBMCs) of lupus patients significantly increased, and was positively correlated with disease activity." (PMID 36057687, 2022).
lupus (continued). "Accordingly, we also observed that the cells with the highest AIM2 levels were AIM2+ TFH‐like cells (CD4+PD1+Bcl6+AIM2+) in lupus patients." (PMID 35343082, 2022). "It is quite fascinating that both TFH cells and B cells adapt to the lupus environment by employing epigenetic regulation via upregulating AIM2, despite their responses to different triggers." (PMID 35538881, 2022). "Using the AIM2 inhibitor class C1 decoy oligodeoxynucleotides (ODNs) in lupus-prone (NZB x NZW) F1 mice resulted in a delayed onset of glomerulonephritis and prolonged survival." (PMID 35664004, 2022). "In lupus macrophages, AIM2 has been found to be directly activated by cytoplasmic DNA, consequently activating inflammasome responses and cell death." (PMID 35343082, 2022). "Up to this point, our findings revealed a potential function of AIM2‐mediated TFH cells in lupus pathogenesis." (PMID 35343082, 2022). "Here, we report increased expression of AIM2 in human tonsil memory and germinal center (GC) B cells and in memory B cells and plasma cells from the circulation and skin lesions of lupus patients." (PMID 34521812, 2021). "The activation of AIM2 relates myelofibrosis and systemic lupus erythematosus (SLE), since in both cases the aberrant macrophage maturation is related to the role of this inflammasome as a sensor of dsDNA deriving from apoptotic cells." (PMID 33429941, 2021). "Here, we first described an increased level of AIM2 in human tonsil memory and GC B cells and in memory B cells and plasma cells from the peripheral blood from lupus patients." (PMID 34521812, 2021). "Surprisingly, AIM2 is expressed by B cells, and higher AIM2 expression is observed in the B cells from lupus patients." (PMID 34521812, 2021). "Unsurprisingly, IL-10 reduced the DNA methylation level of AIM2, lupus B cells showed a lower level of DNA methylation of AIM2, and decreased DNA methylation was found in active SLE B cells." (PMID 34521812, 2021). "Together, our findings reveal that AIM2 is highly expressed in the B cells of lupus patients and promotes B-cell differentiation by modulating the Bcl-6–Blimp-1 axis, providing a novel target for SLE treatment." (PMID 34521812, 2021). "In lupus, increased AIM2 expression was positively correlated with the disease's SLEDAI score and was regulated by body hormones." (PMID 31427885, 2019). "Male hormones can increase the expression of AIM2 in cells, and consistently, a higher level of AIM2 mRNA in macrophages was observed in male patients with lupus compared with female patients." (PMID 31427885, 2019). "AIM2 was highly expressed in B cells of lupus patients and mice models." (PMID 39917309, 2025). "Notably, diminished AIM2 expression in a murine lupus model corresponded to improvement in lupus symptoms." (PMID 39100670, 2024). "Studies have indicated that AIM2 may also serve a protective role in lupus by negatively regulating type I IFN production." (PMID 37081890, 2023). "Further study may focus on whether AIM2 can promote the inflammatory cell infiltration in skin and our study paved the way for the potential of AIM2‐targeted treatment in skin lesions of lupus patients." (PMID 35343082, 2022). "Also, AIM2 expression was increased in kidney macrophages of lupus mice, and knockdown of AIM2 significantly ameliorated tissue damage by inhibiting macrophages activation." (PMID 36057687, 2022). "Examining the blood of people with lupus revealed that one in three of them made antibodies that could stick to AIM2." (PMID 35608258, 2022). "Since reduced DNA methylation in the AIM2 promoter in CD4+ T cells has been observed in lupus patients, we wondered whether DNA methylation‐modulated AIM2 might regulate TFH cell differentiation, which can exert pathogenic effects on SLE." (PMID 35343082, 2022).
lupus (continued). "Additionally, we found higher expression of AIM2‐TFH in SLE patients and further confirmed that CD4+ T cell‐Aim2 accelerates lupus symptoms mediated by regulation of TFH cell differentiation in disease models." (PMID 35343082, 2022). "The loss of AIM2 in B cells reduced KLH-induced antibody production and ameliorated lupus symptoms." (PMID 34521812, 2021). "Furthermore, reduction of AIM2 expression markedly alleviated lupus-like symptoms through inhibiting macrophage activation and inflammatory responses in DNA-induced lupus mice." (PMID 31871956, 2019). "Moreover, the levels of the p202 protein in BMDMs from non lupus-prone (B6) and a lupus-prone strain of mice (the NZB) were inversely correlated with the activation of caspase-1 by the AIM2 inflammasome." (PMID 22046441, 2011). "Prior studies have reported elevated dsDNA levels in the peripheral blood of systemic lupus erythematosus (SLE) patients, alongside heightened AIM2 mRNA expression in PBMCs." (PMID 39100670, 2024). "In the context of T follicular helper (TFH) cell-mediated systemic lupus erythematosus (SLE), AIM2 was found to promote TFH cell differentiation and IL-21 production via the c-myofascial fibrosarcoma (c-MAF) signaling pathway." (PMID 39600708, 2024). "Due to its ability to recognize host DNA, AIM2 involves the pathogenesis of systemic lupus erythematosus (SLE) and tumorigenesis." (PMID 35883561, 2022). "The increased expression of IL21, TET2, AIM2 and c‐MAF and the positive correlation of AIM2 with IL21 or c‐MAF in SLE patients support the potential contribution of the IL‐21‐TET2‐AIM2‐c‐MAF axis to lupus development." (PMID 35538881, 2022). "Previous evidence has indicated that AIM2 in innate immune cells is closely related to disease severity in SLE patients and facilitates mouse disease symptoms in an apoptotic DNA‐induced lupus model." (PMID 35343082, 2022). "As we observed greater numbers of AIM2+ B cells in SLE patients, we further investigated the effect of AIM2 in lupus disease progression." (PMID 34521812, 2021). "As expected, AIM2 expression was increased in the dermis of skin lesions from discoid lupus erythematosus (DLE) patients compared with that from SLE patients and normal control (NC) subjects (n = 3)." (PMID 34521812, 2021). "The most direct evidence shows a contribution of AIM2 to the pathogenesis of Lupus nephritis in an apoptotic lymphocyte DNA-induced SLE model." (PMID 24367371, 2013). "Our results have identified a role of AIM2 in promoting the TFH cell response and further revealed that the IL‐21‐TET2‐AIM2‐c‐MAF signalling pathway is dysregulated in lupus pathogenesis, which provides a potential therapeutic target for SLE." (PMID 35343082, 2022). "In skin lesions, higher mRNA levels of AIM2 and TFH‐related genes, including BCL6, IL21 and STAT3, were found in lupus patients than in NCs." (PMID 35343082, 2022). "In fact, IL‐21 increases the recruitment of TET2 to the BCL6 promoter region in lupus patients, while interferon (IFN)‐α, the signature cytokine for lupus, also increases AIM2 levels, albeit to a lesser degree." (PMID 35538881, 2022). "The NA-sensing pathway generated by our analysis also included absent in melanoma 2 (AIM2), a cytosolic dsDNA-sensing protein that activates the inflammasome, further emphasizing the plausible role of this pathway in initiating lupus inflammation." (PMID 34946847, 2021). "Except for naive B cells, memory B cells and plasma cells from lupus patients showed higher expression of AIM2 compared with HCs, suggesting that AIM2 might contribute to the pathogenesis of SLE." (PMID 34521812, 2021). "Indeed, increased activation of AIM2 inflammasome has been found in unstimulated macrophages collected from male SLE patients, leading to abnormal macrophage maturation and thereby contributing to the immune dysregulation of severe lupus nephritis." (PMID 34014039, 2021).